PDCD1 (programmed cell death 1)
Description:
Inhibitory receptor on antigen activated T-cells that plays a critical role in induction and maintenance of immune tolerance to self. Delivers inhibitory signals upon binding to ligands CD274/PDCD1L1 and CD273/PDCD1LG2. Following T-cell receptor (TCR) engagement, PDCD1 associates with TCR-CD3 in the immunological synapse and directly inhibits T-cell activation. Suppresses T-cell activation through the recruitment of PTPN11/SHP-2: following ligand-binding, PDCD1 is phosphorylated within the ITSM motif, leading to the recruitment of the protein tyrosine phosphatase PTPN11/SHP-2 that mediates dephosphorylation of key TCR proximal signaling molecules, such as ZAP70, PRKCQ/PKCtheta and CD247/CD3zeta. The PDCD1-mediated inhibitory pathway is exploited by tumors to attenuate anti-tumor immunity and escape destruction by the immune system, thereby facilitating tumor survival. The interaction with CD274/PDCD1L1 inhibits cytotoxic T lymphocytes (CTLs) effector function. The blockage of the PDCD1-mediated pathway results in the reversal of the exhausted T-cell phenotype and the normalization of the anti-tumor response, providing a rationale for cancer immunotherapy.
Synonyms: hPD-1; CD279; PD1; hSLE1; PD-1; ADMIO4; AIMTBS; SLEB2; hPD-l
Tractability: Small molecule: a structure with a bound ligand is known; a high-quality ligand is known. Antibody: an approved drug acts on it; UniProt places it where antibodies can reach, with high confidence; its Gene Ontology location is reachable by antibodies, with high confidence; UniProt predicts a signal peptide or a membrane-spanning region. PROTAC: it is named in the literature on targeted protein degradation; UniProt records ubiquitination sites on it; a small molecule that binds it is known. Other modalities: a drug acting on it is in phase 2 or 3 trials.
Target class: Surface antigen
Gene: Protein-coding gene on chromosome 2 (241,849,884 to 241,858,894, reverse strand). Ensembl gene ENSG00000188389.
Subcellular location: Cell membrane
Pathways (Reactome):
Immune System: Co-inhibition by PD-1; PD-L1(CD274) glycosylation and translocation to plasma membrane
Disease: Potential therapeutics for SARS
Gene Ontology:
Molecular function: protein binding; signaling receptor activity; transmembrane signaling receptor activity
Biological process: negative regulation of T cell activation; negative regulation of T cell mediated immune response to tumor cell; negative regulation of T cell receptor signaling pathway; apoptotic process; humoral immune response; negative regulation of immune response; negative regulation of inflammatory response; regulation of immune response; negative regulation of multicellular organismal process
Cellular component: plasma membrane; external side of plasma membrane; membrane
Genetic constraint (gnomAD): Loss-of-function variants: 10 observed, 19.04 expected, observed/expected ratio (o/e) 0.53, 90% interval 0.32 to 0.89. The upper end of that interval is the gene's LOEUF score, 0.89, which puts it in group 3 of 6, group 1 being the genes least tolerant of losing a copy. Missense variants: 312 observed, 388.72 expected, observed/expected ratio (o/e) 0.8, 90% interval 0.73 to 0.88. Synonymous variants: 167 observed, 166.5 expected, observed/expected ratio (o/e) 1, 90% interval 0.88 to 1.14.
Gene-disease validity (ClinGen):
ClinGen rates the evidence that PDCD1 causes each of these diseases.
autoimmune disease (autosomal recessive): Limited. A disorder resulting from loss of function or tissue destruction of an organ or multiple organs, arising from humoral or cellular immune responses of the individual to their own tissue constituents.
Homologues: Orthologues: chimpanzee PDCD1 (99% identical), macaque PDCD1 (96% identical), guinea pig PDCD1 (67% identical), rabbit PDCD1 (64% identical), pig PDCD1 (63% identical), rat Pdcd1 (61% identical), mouse Pdcd1 (60% identical), dog PDCD1 (53% identical).
Diseases named in the same sentence as PDCD1 in open-access papers:
PDCD1 is named in the same sentence as 395 diseases in open-access papers, as found by Europe PMC text mining. Sharing a sentence is not in itself a finding about the gene and the disease. The quoted sentences say what the papers report.
melanoma (512 papers, 2014 to 2026). A malignant, usually aggressive tumor composed of atypical, neoplastic melanocytes. "These LD findings are particularly relevant for evaluating the potential association of specific PDCD1 variant combinations with differential susceptibility or protection to melanoma in the study sample." (PMID 40869918, 2025). "Studies have shown that global DNA hypomethylation in melanoma cells is associated with constitutive expression of immune evasion genes, including PDCD1." (PMID 40869918, 2025). "Several studies have shown that elevated PDCD1 expression in tumors can be associated with immune evasion and poor prognosis in various cancers, including melanoma." (PMID 40869918, 2025). "ICIs that block cytotoxic T lymphocyte-associated protein 4 (CTLA-4) or programmed cell death 1 (PD-1) or its ligand PD-L1 are approved for the treatment of a variety of cancers, including melanoma, non-small cell lung carcinoma, and cervical cancer." (PMID 40806825, 2025). "This study aimed to evaluate the association of PDCD1 variants (rs2227982, rs36084323, rs7421861) and its relative gene expression with melanoma in a Mexican population." (PMID 40869918, 2025). "Genetic variants in PDCD1, such as rs2227982 G>A, rs36084323 C>T, and rs7421861 A>G, have been associated with susceptibility to various types of cancer, including melanoma, by altering the function or expression of the PD-1 protein." (PMID 40869918, 2025). "Analysis of single-cell datasets revealed distinct human melanoma-infiltrating CD8+ T-cell clusters expressing genes associated with effector T-cell function but with distinguishing expression of CX3CR1 or PDCD1." (PMID 38881188, 2024). "In a melanoma-bearing mouse model, circadian oscillations were reported in PD-1, Pdcd1, and in the PD-L1-encoding Cd274 gene." (PMID 37626878, 2023). "OXPHOS metabolism of cancer cells is associated with T-cell exhaustion and poor response to Programmed cell death 1 (PD-1) blockade immunotherapy in melanoma due to high oxygen consumption resulting in hypoxia in the TME." (PMID 35281061, 2022). "This case highlights the challenges involving programmed cell death 1 blockade in high-risk melanoma, in which infections, lymphoproliferative disorders, and sarcoidosis can mimic disease progression and trigger immune-related adverse events." (PMID 34233733, 2021). "For example, the single cell RNA sequencing of tumoral T cells from melanoma and lung cancer indicated that T cells expressed genes such as PDCD1 and LAG3 that are associated with T cell dysfunction." (PMID 32117960, 2020). "Antibodies directed against the cytotoxic T-lymphocyte-associated antigen 4 (CTLA-4) receptor or programmed cell death-1 (PD-1) receptor have revolutionized the systemic therapy of advanced melanoma." (PMID 31506076, 2019). "Antibodies blocking PD-L1 or programmed cell death-1 (PD-1) have increased patient survival in carcinomas with significant mutational burden such as melanoma, lung, and bladder cancers." (PMID 30898149, 2019). "We describe the first case to our knowledge of a patient with widespread melanoma metastases involving the bone marrow causing myelophthisis who responded to immune checkpoint inhibition with the anti-programmed cell death-1 (PD-1) inhibitor pembrolizumab." (PMID 28428883, 2017). "We describe a patient with widespread melanoma metastases involving the bone marrow causing myelophthisis and pancytopenia who responded to immune checkpoint inhibition with the anti-programmed cell death-1 (PD-1) inhibitor pembrolizumab." (PMID 28428883, 2017). "One of the most remarkable immunomodulatory therapies of recent times is currently licensed for melanoma treatment – antibody-based inhibition of the immune checkpoints programmed cell death 1 (PD-1) and cytotoxic T lymphocyte-associated antigen 4 (CTLA-4)." (PMID 27301245, 2016). "However, to date, little research has been conducted on PDCD1 variants and their impact on melanoma in this population." (PMID 40869918, 2025).
melanoma (continued). "Such regional and ancestral variation could influence allele frequencies of PDCD1 polymorphisms, and consequently their association with melanoma risk." (PMID 40869918, 2025). "ICB therapies, including programmed cell death-1, its ligand, and cytotoxic T-lymphocyte associated protein-4, have been approved for the treatment of multiple carcinoma types, such as advanced melanoma, renal cell carcinoma, non–small cell lung cancer, and BLCA." (PMID 35174161, 2021). "In particular, inhibitors of the cytoplasmic serine/threonine kinase BRAF and the immune-checkpoint targeted agents, anti-cytotoxic T-lymphocyte-associated antigen 4 (CTLA-4), and anti-programmed cell death 1 (PD-1) inhibitors have been approved for the treatment of advanced melanoma." (PMID 30693134, 2018). "Additionally, directly suppressing XBP1 in melanoma cells enhances the effectiveness of immunotherapy when treated with antibodies targeting proteins involved in the programmed cell death 1 (PD‐1) and cytotoxic T cell lymphocyte‐associated antigen 4 (CTLA‐4) pathways." (PMID 40035165, 2025). "However, it has been demonstrated that in mouse melanoma models, the variation in treatment efficiency with timing of administration aligns with increased tumour-associated macrophages and rhythmic expression of the Pdcd1 gene Pdcd1 (encoding PD-1)." (PMID 40075745, 2025). "Furthermore, the expression of ICIs between high- and low-risk melanoma patients were analyzed, indicating that the expression of immune-regulatory proteins (IRPs) such as PD-1 (PDCD1), PD-L1 (CD274), CTLA-4, HAVCR2 (TIM3), CD8, and LAG3 was significantly lower in the high-risk group (p < 0.05)." (PMID 35326741, 2022). "A study using murine B16-F10 melanoma cells showed marked expression of Pdcd1, comparable to that of resting T cells and detectable by qPCR and flow cytometry." (PMID 40869918, 2025). "Considering that the reference group was calibrated to a value of 1, this result indicates a 1.42-fold increase in PDCD1 expression in the melanoma group." (PMID 40869918, 2025). "This integrative analysis in an underrepresented population adds a novel perspective to the current understanding of PDCD1 in melanoma." (PMID 40869918, 2025). "New treatment options are needed for patients with metastatic anti–programmed cell death 1 (PD‐1)–resistant melanoma." (PMID 40753466, 2025). "The regulation of PDCD1 expression and its impact on melanoma cannot be understood in isolation from the tumor microenvironment (TME), which orchestrates immune responses through a dense regulatory network." (PMID 40869918, 2025). "Recently, however, immune checkpoint inhibitors such as anti-programmed cell death-1 antibodies have been suggested to improve the prognosis of malignant melanoma." (PMID 40356806, 2025). "Nonetheless, a higher expression level of PDCD1 was identified in individuals with melanoma, suggesting a potential immunological involvement of this gene in the context of the disease." (PMID 40869918, 2025). "Understanding this complexity is essential for interpreting PDCD1’s role in melanoma and designing future immunotherapeutic strategies." (PMID 40869918, 2025). "The relative expression of the PDCD1 gene was assessed in samples from melanoma patients and controls." (PMID 40869918, 2025). "The anti-PD1 therapy for melanoma offered better survival outcomes when the expression of PDCD1, TIGIT, and HAVCR2 was high." (PMID 40076932, 2025). "Vidutolimod alone or in combination with pembrolizumab had an acceptable safety profile, and showed antitumor activity in patients with programmed cell death 1 blockade–resistant melanoma." (PMID 40753466, 2025). "Herein, a magnetic resonance imaging (MRI)-visualized PTT/PDT agent (SIDP NMs) was constructed, and the efficacy of its multimodal combination with a programmed cell death 1 (PD-1) inhibitor in the treatment of melanoma and metastases was studied." (PMID 38525327, 2024).
melanoma (continued). "Treatments with ICIs, including antibodies against cytotoxic T-lymphocyte antigen 4 (CTLA-4) and programmed cell death-1 (PD-1), activate the immune system and have shown anti-tumor effects with increasing survival rates in advanced melanoma patients." (PMID 38611018, 2024). "The development of immune checkpoint inhibitors (ICIs) targeting programmed cell death-1 (PD1) pathways has changed the landscape of melanoma therapy." (PMID 39125477, 2024). "RTP4 has also been reported that it is significantly associated with immune cell infiltration and immune checkpoint encoding genes (PDCD1, TIM-3, and LAG3) in melanoma." (PMID 37152371, 2023). "WT or Pdcd1−/− mice were engrafted with B16F10 melanoma cells (B16), and the tumor growth was monitored." (PMID 37098069, 2023). "Clinical trials testing LAG-3 inhibitors in combination with programmed cell death 1 (PD-1) inhibitors have shown significant improvements in progression-free survival (PFS) compared to PD-1 inhibition alone in patients with melanoma." (PMID 37808404, 2023). "Of note, we validated the role of RAC1, an ERG, in modulating the behavior of melanoma cells and regulating the expression of programmed cell death-1 (PD-1)/programmed death-ligand 1 (PD-L1) and cytotoxic T-lymphocyte-associated antigen 4 (CTLA4) in vitro." (PMID 37217516, 2023). "Immune checkpoint molecules (such as PDCD1, CD274, and CTLA4) and co-stimulatory molecules were also highly expressed in low-risk melanoma group (FDR-adjusted P < 0.05, one-sided Wilcoxon rank-sum test)." (PMID 37620409, 2023). "Here we perform super-resolution immunofluorescence microscopy of human melanoma tissue sections to examine the spatial organization of the immune checkpoint inhibitor programmed cell death 1 (PD-1)." (PMID 37539093, 2023). "Remarkably, also mRNA expressions of CD274/PD-L1 and PDCD1/PD-1 were significantly down-regulated in pDCs exposed to melanoma secretome suggesting that pDCs become hyporesponsive to TLR-mediated stimulation when exposed to CM secretome." (PMID 38239354, 2023). "As an illustration, a notable example is the demonstrated influence of the gut microbiome on modulating the response of melanoma to anti-programmed cell death 1 protein (PD-1) immunotherapy." (PMID 38132866, 2023). "For example, advanced melanoma patients treated with BRAFi or BRAFi/MEKi combination exhibited increased expression of programmed cell death 1 (PD-1) and its ligand, PD-L1." (PMID 37834284, 2023). "In melanoma, MEX3B downregulation is associated with antibodies against programmed cell death 1 (PD-1), while overexpression of this protein can inhibit T cell-mediated tumour elimination." (PMID 36507941, 2023). "An analysis of The Cancer Genome Atlas (TCGA) database on RNA profiles obtained from melanoma, colon cancer and ovarian cancer revealed that PDCD1 is positively correlated with SLC43A2." (PMID 37147330, 2023). "Therapeutic antibodies in immune checkpoint therapies targeting programmed cell death-1 (PD-1) have been approved as mature treatment options for melanoma patients." (PMID 36034849, 2022). "GSK3 blockers, on the other hand, promote tumor elimination in animal melanoma models by suppressing the PDCD1 gene." (PMID 36363529, 2022). "Immune checkpoint inhibitors (ICIs) targeting programmed cell death-1 (PD-1) or cytotoxic T lymphocyte-associated protein-4 (CTLA-4) have achieved tumor regression in several cancers, such as melanoma, lung cancers, and Hodgkin lymphoma." (PMID 35572595, 2022). "T-cell inhibitory molecules, such as the programmed cell death-1 (PD-1) antibody, which was first licensed for the treatment of malignancies melanoma, are used to block the immunological checkpoint." (PMID 36654821, 2022). "Immune checkpoint inhibitors (ICIS) such as ipilimumab (CTLA-4 inhibitor) and nivolumab (PDCD-1 inhibitor) significantly improve the overall survival rates of patients with melanoma and advanced liver cancer." (PMID 35769911, 2022).